TCL1A (TCL1 family AKT coactivator A)
Description:
Enhances the phosphorylation and activation of AKT1, AKT2 and AKT3. Promotes nuclear translocation of AKT1. Enhances cell proliferation, stabilizes mitochondrial membrane potential and promotes cell survival.
Synonyms: TCL1
Tractability: PROTAC: its protein half-life has been measured.
Gene: Protein-coding gene on chromosome 14 (95,709,947 to 95,714,196, reverse strand). Ensembl gene ENSG00000100721.
Subcellular location: Cytoplasm; Nucleus; Microsome; Endoplasmic reticulum
Subcellular location (Human Protein Atlas): Cytosol; Endoplasmic reticulum; Nucleoplasm
Gene Ontology:
Molecular function: identical protein binding; protein binding; protein kinase binding; protein serine/threonine kinase activator activity
Biological process: intracellular signal transduction
Cellular component: cytosol; endoplasmic reticulum; nucleoplasm; nucleus; cytoplasm
Genetic constraint (gnomAD): Loss-of-function variants: 9 observed, 17.05 expected, observed/expected ratio (o/e) 0.53, 90% interval 0.32 to 0.92. The upper end of that interval is the gene's LOEUF score, 0.92, which puts it in group 3 of 6, group 1 being the genes least tolerant of losing a copy. Missense variants: 139 observed, 157.43 expected, observed/expected ratio (o/e) 0.88, 90% interval 0.77 to 1.02. Synonymous variants: 69 observed, 67.31 expected, observed/expected ratio (o/e) 1.03, 90% interval 0.84 to 1.25.
Cancer hallmarks: escaping programmed cell death (promotes); proliferative signalling (promotes)
Homologues: Orthologues: chimpanzee TCL1A (99% identical), macaque TCL1A (88% identical), pig TCL1A (54% identical), mouse Tcl1 (48% identical), rat Tcl1a (41% identical), dog TCL1A (32% identical). Paralogues in human: MTCP1 (35% identical), TCL1B (32% identical).
Diseases named in the same sentence as TCL1A in open-access papers:
TCL1A is named in the same sentence as 53 diseases in open-access papers, as found by Europe PMC text mining. Sharing a sentence is not in itself a finding about the gene and the disease. The quoted sentences say what the papers report.
lymphoma (12 papers, 2012 to 2025). A malignant (clonal) proliferation of B- lymphocytes or T- lymphocytes which involves the lymph nodes, bone marrow and/or extranodal sites. "TCL1A encodes the T-cell leukemia/lymphoma 1A oncoprotein, which contributes to the development and progression of chronic lymphoblastic leukemia and lymphomas." (PMID 40363705, 2025). "The gene TCL1A (T Cell Leukemia/Lymphoma 1A) encoding the 14 kDa TCL1A protein is located at chromosome 14q32.1." (PMID 33760860, 2021). "In humans and mice, overexpression of TCL1A due to chromosomal rearrangement of the TCL1A gene to the T cell receptor locus causes mature T cell leukemia and lymphoma." (PMID 26299617, 2015). "In addition to diagnostic value, TCL1A mRNA and protein expression carry prognostic information in several leukemias/lymphomas." (PMID 34771618, 2021). "TCL1A overexpression also occurs in B lineage cells and can lead to multiple types of lymphoma arising from pre-GC differentiation stages." (PMID 34206047, 2021). "Notably, 6/31 autosomal genes are associated with hematological malignancies, including TCL1A (MIM * 186960), a known leukemia/lymphoma risk factor." (PMID 36460769, 2022). "Indeed, gene markers known to be highly expressed by transitional and naïve B cells such as Membrane Spanning 4-Domains A1 (MS4A1), CD79B, and T-Cell Leukemia/Lymphoma 1A (TCL1A) were enriched in samples from ITx patients." (PMID 31134051, 2019). "Indeed, TCL1A overexpression is a common finding in both leukemia and lymphoma, although amplification of this gene was also reported in a pre-malignant cervical lesion." (PMID 26299617, 2015). "TCL1A also represses the expression of truncated receptor-type protein tyrosine phosphatase (PTPROt), a phosphatase expressed in naïve B cells that represses lymphoma in Eμ-TCL1A mice, and regulates BCR signals by modulating the activity of tyrosine kinases, including Lyn, Syk and ZAP70." (PMID 34206047, 2021). "Those of pre-GC derivation, such as B-cell acute lymphoblastic leukemia/lymphoma (ALL/LBL) and mantle cell lymphoma (MCL), are highly TCL1A positive." (PMID 34771618, 2021). "The expression of TCL1A is deregulated in lymphocytic leukemia (B-CLL) and most lymphomas, which involve several signaling pathways, such as the phosphatidylinositol 3 kinase (PI3K) and nuclear factor-kB (NF-kB) pathways." (PMID 33603736, 2020). "All spleen samples involved by other lymphoma/leukemia subtypes (five FL, one B-CLL, one MCL, one HCL, one LPL) stained positive for TCL1A." (PMID 23064660, 2012). "Second in the ranking was TCL1A, an oncoprotein in T cell leukemias, lymphomas, CLL and several nonhematological cancers." (PMID 37932435, 2023). "However, it remains unclear whether these leukemias/lymphomas are centrally (co) initiated by TCL1A (likely the case in T-PLL) and whether they retain a TCL1A dependence." (PMID 34771618, 2021). "Although not widely used, TCL1A is a helpful marker in lymphoma characterization." (PMID 23064660, 2012).
leukemia (9 papers, 2009 to 2024). A malignant (clonal) hematologic disorder, involving hematopoietic stem cells and characterized by the presence of primitive or atypical myeloid or lymphoid cells in the bone marrow and the blood. "The adverse clinical outcomes in some solid tumors and leukemias in association with high TCL1A expression are likely to a considerable part the result of the TCL1A-mediated augmented activity of AKT contributing to enhanced proliferation and multi-nodal resistance." (PMID 34771618, 2021). "Abnormal expression of TCL1A gene in mouse B-cells led to a leukemia phenotype similar to aggressive human CLL." (PMID 38435839, 2024). "In line with this, high TCL1A was correlated with shorter leukemia-specific survival in MCL, as well as with clinical stage and shorter overall survival in DLBCL." (PMID 34771618, 2021). "This improved biological understanding forms the basis for future work on approaches to interfere in tumorigenic processes mediated by TCL1A or to target this molecule directly, i.e., in TCL1A-overexpressing leukemias." (PMID 34771618, 2021). "As another source of TCL1A-regulating milieu-derived stimuli, direct cell–cell contact of leukemia with bone marrow stromal cells (BMSCs) was identified." (PMID 34771618, 2021). "In several leukemia mouse models, Dnmt3a has been identified as a tumor suppressor, therefore suggesting a meaningful impact of TCL1A-mediated inhibition of DNMT3A during leukemogenesis." (PMID 34771618, 2021). "In this cluster, the over-expression of PAX5 and TCL1A could also indicate presence of malignant immune cells as these genes are often found in leukemia and likely to contribute to oncogenesis BCL6." (PMID 32070336, 2020). "Similarly, we showed that PAX5, EBF1, CD72 and TCL1A are tightly correlated in the capacity to distinguish lymphoblastic and myeloblastic characteristics also in the presence of MLL mutations illustrating the importance of B-cell receptor signaling pathway in this subset of leukemias." (PMID 19549311, 2009). "Deregulation events of CSRP2, TCL1A, CD72 and EBF genes in acute pediatric leukaemia have been previously reported using gene expression profiling." (PMID 19549311, 2009).
T-cell leukemia (9 papers, 2014 to 2025). A malignant disease of the T-lymphocytes in the bone marrow, thymus, and/or blood. "However, TCL1A levels in other tumors, such as T-cell leukemia and B-cell lymphoma, have been demonstrated to be associated with a poor tumor prognosis." (PMID 38764038, 2024). "The consistent effect of TCL1A on the proliferation of tumor cells in T-cell leukemia and B-cell lymphoma further supports its universal ability to enhance cell proliferation." (PMID 38764038, 2024). "TCL1A is a known coactivator of AKT that has been extensively studied in T-cell leukemia and B-cell lymphoma." (PMID 38764038, 2024). "In T-cell leukemia and B-cell lymphoma, TCL1A is primarily expressed in tumor cells, where it promotes tumor cell proliferation and leads to a poor prognosis." (PMID 38764038, 2024). "The most significant SNP marker at 14q32.13 (rs117410836) is located near an uncharacterized long non-coding RNA (lncRNA; LINC02318), GLRX5 (glutaredoxin 5), and members of the T-cell leukemia (TCL) gene family (TCL1A, TCL1B, and TCL6)." (PMID 30305637, 2018). "Consequently, we modeled the specific impact of TCL1A after introduction into the ATM-biallelic mature T-cell leukemia lines HH (inducible) and Hut78 (stable)." (PMID 29449575, 2018). "In addition, some endometriotic lesions over-express T-cell leukemia/lymphoma protein 1A (TCL1A), a known marker of immature T- and B-cells and another proto-oncogene causally associated with T-cell leukemia in humans." (PMID 25593975, 2014). "The pathogenesis of T-PLL involves rearrangement of the TCR, located on chromosome 14q) and juxtaposition with T-cell leukemia (TCL) genes, leading to the aberrant expression of TCL1A, TCL1B, or MTCP1 oncogenes in approximately 95% of cases." (PMID 41259500, 2025).
B-cell lymphoma (7 papers, 2009 to 2024). "Our data support the use of TCL1A in the panel of diagnostic markers used in the differential diagnosis of splenic low-grade B-cell lymphoma; a possible prognostic value, however, needs a larger series to be established." (PMID 23064660, 2012). "For example, a super-enhancer within TCL1A was identified in high-grade B-cell lymphoma, mantle cell lymphoma and small lymphocytic lymphoma." (PMID 33859327, 2021). "The majority of EBV-infected B-cell non-Hodgkin lymphomas (B-NHL) appear to be positive for TCL1A to a higher degree than their EBV-negative counterparts." (PMID 34771618, 2021). "In contrast to the findings in iPSCs, the introduction of TCL1A into mature B-cell lymphoma lines led to reduced aerobic glycolysis and a higher rate of oxygen consumption coupled to ATP-synthesis." (PMID 34771618, 2021). "Moreover, TCL1A has been proposed as a potential therapeutic target in B cell lymphoma necessary for malignant B cell survival, indicating its association with B cells." (PMID 37791059, 2023). "However, post-GC-derived AIDS-DLBCL expresses TCL1A at a frequency equivalent to naïve/GC-derived B-cell lymphomas in immune-competent individuals, although often expressing type II/III latency." (PMID 34771618, 2021). "Given that TCL1A has been reported as an important gene in B cell lymphomas, these findings suggest that TCL1A might be a novel marker of naïve B cells." (PMID 33287869, 2020).
breast carcinoma (6 papers, 2012 to 2025). "Another potential biological pathway involves SNPs that created an estrogen response element near the 3’ end of the T-cell leukemia 1A (TCL1A) gene and was associated with increased musculoskeletal pain in women on adjuvant AI for breast cancer." (PMID 34385978, 2021). "The effect of TCL1A polymorphisms in HR+ postmenopausal breast cancer patients treated with letrozole needs further research to confirm its effect on other independent populations." (PMID 33760860, 2021). "Therefore, we indended to understand the clinical relevance of TCL1A genetic polymorphisms on the development of letrozole-induced ‘specific’ AEs in postmenopausal HR+ breast cancer patients of South Indian ancestry." (PMID 33760860, 2021). "In a recent genome-wide association study, we identified SNPs - including one that created an estrogen response element near the 3' end of the T-cell leukemia 1A (TCL1A) gene - that were associated with musculoskeletal pain in women on adjuvant AI therapy for breast cancer." (PMID 22405131, 2012). "Thus, it appears unlikely that polymorphisms in TCL1A loci may be a robust predictor for AEs in HR+ breast cancer patients treated with letrozole." (PMID 33760860, 2021). "Our findings suggest that TCL1A gene polymorphisms may not play any role in the prediction of letrozole-induced AEs in South Indian HR+ breast cancer patients." (PMID 33760860, 2021). "Patients with breast cancer who had low levels of expression of the genes CD19, CD79A, IFIT5, MS4A1, and TCL1A had shorter disease-free survival times." (PMID 37684436, 2023). "However, a small clinical study of 198 postmenopausal HR+ breast cancer patients was not able to find an association between patients with AIMSS and TCL1A polymorphisms." (PMID 34385978, 2021).
T-prolymphocytic leukemia (6 papers, 2018 to 2025). "The pathogenesis of T-cell prolymphocytic leukemia involves recurrent genetic alterations, including TCL1A rearrangements and ATM mutations, which promote genomic instability." (PMID 41259500, 2025). "In chronic lymphocytic leukemia and in T-prolymphocytic leukemia, TCL1A has been implicated in the pathogenesis of these conditions, and high-level TCL1A expression correlates with more aggressive disease characteristics and poorer patient survival." (PMID 34771618, 2021). "GPM confirmed an inverted insertion of the 14q32.13-q32.2 fragment containing TCL1A into TRA/D at 14q11.2, resulting in TRA/D::TCL1A fusion, consistent with a diagnosis of T-prolymphocytic leukemia (T-PLL)." (PMID 41374977, 2025). "Chromosomal rearrangements involving 14q11 in T-Prolymphocytic leukaemia (T-PLL) deregulate TCL1A due to a TRA::TCL1A rearrangement." (PMID 38835967, 2024).
B-cell chronic lymphocytic leukemia (5 papers, 2012 to 2021). "In B-cell chronic lymphocytic leukemia, ATM was found to physically interact with TCL1A protein, and this association activates the NF-κB pathway in the regulation of apoptosis." (PMID 33859327, 2021). "T Cell Leukemia/Lymphoma 1A is expressed during B-cell differentiation and, when over-expressed, acts as an oncogene in mouse (Tcl1a) and human (TCL1A) B-cell chronic lymphocytic leukemia (B-CLL) and T-cell prolymphocytic leukemia (T-PLL)." (PMID 30286151, 2018).
Immunodeficiency (4 papers, 2018 to 2025). Failure of the immune system to protect the body adequately from infection, due to the absence or insufficiency of some component process or substance. "Finally, TCL1A was associated with abc_transporters, oocyte_meiosis, and primary_immunodeficiency." (PMID 41403942, 2025). "From the data on the impact of EBV on TCL1A levels, we postulate that generally, TCL1A expression is also influenced by severe immune dysfunction." (PMID 34771618, 2021).
B-cell acute lymphoblastic leukemia (2 papers, 2021 to 2024). A neoplasm of lymphoblasts committed to the B-cell lineage, typically composed of small to medium-sized blast cells. "Furthermore, a negative correlation of TCL1A and expression of the ETS Variant TF 6 (ETV6) in BPDCN and in B-cell acute lymphoblastic leukemia (B-ALL) implicates an additional mode of TCL1A transcriptional regulation." (PMID 34771618, 2021).
Burkitt lymphoma (2 papers, 2021 to 2023). A rare form of malignant mature B-cell non-Hodgkin lymphoma. "Among the main oncogenes induced in LCL-AT, we find BCL11A (log2FC 4.20), a modulator of transcriptional repression frequently upregulated in B-cell malignancies or TCL1A (log2FC 3.41), a survival promoting factor strongly associated with Burkitt lymphoma and related to other malignancies." (PMID 34183044, 2021). "In Raji Burkitt lymphoma, TCL1A has been connected with TP63." (PMID 37791059, 2023).
cervical cancer (2 papers, 2015 to 2021). A primary or metastatic malignant neoplasm involving the cervix. "Our analysis revealed that T-cell leukemia/lymphoma 1A (TCL1A) is a novel immune cell expressed marker for predicting improved survival in patients with cervical cancer." (PMID 26299617, 2015). "Our approach identified TCL1A as a novel putative biomarker for predicting survival in patients with cervical cancer." (PMID 26299617, 2015). "Our results suggest that intratumoral TCL1A+ B cells are important for controlling cervical cancer development." (PMID 26299617, 2015). "Based on these findings, we conclude that TCL1A may be a prognostic biomarker for predicting improved survival in patients with cervical cancer." (PMID 26299617, 2015). "In addition, we used multicolor immunofluorescence to demonstrate that TCL1A is expressed by a subpopulation of B cells in cervical cancer." (PMID 26299617, 2015). "Our data indicate that intratumoral B cells may play an important role in controlling cervical cancer, and TCL1A is a potential marker for a beneficial B cell response." (PMID 26299617, 2015). "TCL1A and BTG1, which are highly expressed in B cells from early CRC tumor, are reported as tumor suppressors in cervical cancer and CRC, respectively." (PMID 33463049, 2021). "Remarkably, high CD19 expression was significantly correlated with improved disease-free survival (based on fresh-frozen tumor tissue samples obtained from an additional cervical cancer patient cohort), whereas CD3E, CD20 and TCL1A were not significantly correlated with survival." (PMID 26299617, 2015).
COVID-19 (2 papers, 2021). A disease caused by infection with severe acute respiratory syndrome coronavirus 2. "Moreover, a marked decrease could be found in the proportions of LMPP, CLP, TCL1A pre-B cells, and Pro-B cells from COVID-19 patients with severe cases when compared to the HC group, while only the proportion of LMPP was significantly decreased in mild cases." (PMID 34349096, 2021).
lymphoid neoplasm (2 papers, 2021 to 2023). A neoplasm composed of a lymphocytic cell population which is usually malignant (clonal) by molecular genetic and/or immunophenotypic analysis. "Given the apparently histogenetically fixed expression of TCL1A in lymphoid tumors, the expression of TCL1A harbors important diagnostic information." (PMID 34771618, 2021). "Interestingly, TCL1A would be more likely expected to be involved in lymphoid neoplasms as it plays a role in lymphopoiesis." (PMID 37046792, 2023).
oral squamous cell carcinoma (2 papers, 2024). "To test this hypothesis, we analyzed the gene expression patterns of oral squamous cell carcinoma (OSCC) in the TCGA cohort using heatmaps and observed a positive correlation between the expression of TCL1A and TLS signatures." (PMID 38764038, 2024).
prolymphocytic leukemia (2 papers, 2021 to 2025). A mature B- or T- cell leukemia with progressive clinical course. "TCL1A is associated with precursor T-cell acute lymphoblastic leukemia and prolymphocytic leukemia." (PMID 34367157, 2021).
T-cell acute lymphoblastic leukemia (2 papers, 2021 to 2024). Acute lymphoblastic leukemia of T-cell origin. "Previous studies have shown that the SUP-T11 cell line, derived from adult T-cell acute lymphoblastic leukemia and characterized by the overexpression of TCL1A gene, shares similar features with T-PLL cells." (PMID 39769335, 2024).
bone tumors (1 paper, 2012). "High-level amplification of TGFβ2 (1q41), CCND3 (6p21), WI-6509 (11qtel), SHGC-5557 (12ptel), TCL1A (14q32.1), CREBBP (16q13.3), HIC1 (17p13.3), THRA (17q11.2), AFM217YD10 (17qtel), LAMA3 (18q11.2), RUNX1 (21q22.3) and D22S543 (22q11), was commonly observed in aggressive bone tumors." (PMID 23199169, 2012).
cardiomyopathy (1 paper, 2023). A disease of the heart muscle or myocardium proper. "It is suggested that a decrease in TCL1A levels may contribute to chemo-induced cardiomyopathy by increasing apoptotic sensitivity, decreasing cardiac MDR1, and increasing doxorubicin and intracellular free radical concentrations." (PMID 37684436, 2023).
cervical tumors (1 paper, 2023). "A previous study of the total RNA-seq of flow-sorted samples reported that B cells with TCL1A expression correlated with improved survival time in cervical tumors, suggesting its prediction potential." (PMID 37791059, 2023).
cutaneous T-cell lymphomas (1 paper, 2021). "Hard-to-classify cases of leukemic MTCL, especially those showing similar clinical features, e.g., skin lesions of T-PLL vs. those of primary cutaneous T-cell lymphomas (CTCL) are now nearly unequivocally assigned by means of TCL1A expression." (PMID 34771618, 2021).